MTAP (methylthioadenosine phosphorylase)
Diseases named in the same sentence as MTAP in open-access papers (continued):
Sharing a sentence is not in itself a finding about the gene and the disease.
cancer (continued). "In addition to homozygous deletion (HD), loss of heterozygosity (9p21 LOH) due to hemizygous deletion of CDKN2A and MTAP was observed in 24.6% and 27.8% of cancers, respectively." (PMID 34556668, 2021). "MTAP deletion is a frequent event in a wide variety of human cancers; however, its biological role in tumorigenesis remains unclear." (PMID 32093414, 2020). "Since MTAP is frequently deleted in human cancers due to its chromosomal proximity to CDKN2A, it was also speculated that inhibitors of PRMT5 could be utilized in potential therapy for MTAP/CDKN2A‐deleted tumors." (PMID 33155773, 2020). "MTAP loss often occurs with p16INK4a/CDKN2A deletion, which is prevalent in cancer." (PMID 32824193, 2020). "The MTAP gene encodes 5-methylthioadenosine phosphorylase, which is associated with the purine and methionine salvage pathways, located in the region adjacent to the CDKN2A gene and frequently codeleted in cancers." (PMID 32887687, 2020). "Alarmingly, the function of MTAP in various cancers has been conflicting." (PMID 30701095, 2019). "In the context of MTAP-deleted cancers, our study de-validates RIOK1 kinase function as a target." (PMID 29983885, 2018). "Interestingly, increased methylthioadenosine (MTA) concentration in cancer cells harbouring 5-methylthioadenosine phosphorylase (MTAP) deletions results in decreased H4R3me2 mark and, consequently, arginine methyltransferase 5 (PRMT5) inhibition." (PMID 30356832, 2018). "MTAP resides in close proximity to the CDKN2A locus that encodes the key tumor suppressor proteins p16 and p14 and is frequently co-deleted across a wide range of cancer indications." (PMID 29983885, 2018). "This suggests that losing p16 gives cancer cells a greater growth advantage than retaining MTAP." (PMID 26910893, 2016). "Because elevated polyamines and ODC are common in cancer cells, it has been speculated that this might be important for MTAP’s tumor suppressor function." (PMID 25387827, 2014). "Additionally, MTA accumulation in MTAP-deleted cancers may influence the TME, and PRMT5 has a significant role in T-cell biology." (PMID 40157258, 2025). "Indeed, the higher prevalence of biliopancreatic cancers among MTAP loss cancers emerged as the actual driver of worse prognosis rather than the MTAP loss itself." (PMID 38350716, 2025). "In our study, CB-839 alone did not induce CXCL10 in cancer cells but selectively impaired the growth of MTAP-deficient cancer cells and restored CXCL10 expression under immune co-culture, suggesting a dual mechanism involving both tumor cell-intrinsic cytotoxicity and immune cell-mediated feedback." (PMID 41246302, 2025). "These factors may vary across cancer types with MTAP gene deletion." (PMID 41465382, 2025). "Thus, they fail to harness the elevations of MTA observed in MTAP-deleted cancers." (PMID 40590219, 2025). "Additionally, AG-270 induces DNA damage and impairs DNA repair activity in MTAP-deficient cells, suggesting that MAT2A inhibition could enhance the efficacy of cancer therapies targeting DNA damage responses." (PMID 40430461, 2025). "Up to 15% of patients with malignant neoplasms may have a deletion of MTAP gene." (PMID 41465382, 2025). "Additionally, clinical partial responses have been noted in cancers with CDKN2A/MTAP co-deletions." (PMID 40157258, 2025). "Finally, to investigate the broader potential for AM-9934 to preferentially inhibit viability of MTAP-deleted cancer cells, we determined inhibitor effects on viability across a 24-cell line panel harboring both MTAP WT and MTAP-deleted cell lines from diverse tissue origins." (PMID 40377999, 2025). "In ERG negative carcinomas, the levels of MTAP expression increased markedly with advanced pT stage and classical or quantitative Gleason grade (p < 0.0001 each), and high (3+) MTAP expression was strongly linked to early PSA recurrence (p < 0.0001)." (PMID 40554389, 2025).
cancer (continued). "Therefore, the local cancer MTAP−/− genotype may be suboptimal for clinical efficacy of MAT2a inhibitors." (PMID 38000655, 2024). "However, MTAP-loss CRC was also associated with a higher frequency of alterations in STK11 and KEAP1, which have been linked to immunotherapy resistance in NSCLC and pan-cancer cohorts." (PMID 38330461, 2024). "Thus MTAP-deleted cancer cells are more sensitive to PRMT5 inhibitors." (PMID 38638566, 2024). "Firstly, in MTAP-deficient tumor cells, the absence of the salvage pathway sensitizes cells to inhibitors of de novo purine synthesis and provides an opportunity to specifically target cancer cells." (PMID 36572880, 2022). "Since both HT1080 and MCF-7 cells are derived from MTAP-deleted cancer cells, we were curious as to what the effect of MTAP loss might be on a nontransformed MTAP+ cell line." (PMID 35963436, 2022). "It is also to be noted that MTAP loss is not observed in some cancers like prostate cancer." (PMID 36572880, 2022). "Therefore, EPZ015666 is less effective in MTAP-null cancer cells." (PMID 34006904, 2021). "In transformed DLBCL, the S-methyl-5’-thioadenosine phosphorylase (MTAP) gene encoding for a critical methionine metabolism enzyme is deleted due to its proximity to the tumor suppressor gene CDKN2A, and this phenomenon sensitizes cancer cells to PRMT5 inactivation." (PMID 31681423, 2019). "MTAP is a gene adjacent to CDKN2A on chromosome 9p and is frequently co-deleted with CDKN2A in a wide range of cancers." (PMID 40361368, 2025). "Considering that the incidences of MTAP and CDKN2A/B co-deletion are events affecting 15% of cancers, MTAP has a high potential of being exploited for targeted therapy." (PMID 41439984, 2025). "The co-deletion of an adjacent gene, methylthioadenosine phosphorylase (MTAP), is a common occurrence, observed in around 15% of all cancers." (PMID 39983717, 2025). "Despite showing specific inhibitory effects on MTAP-null tumors, ALA failed in phase II clinical trials (NCT00062283), for inducing hematologic toxicities in patients of different cancer types." (PMID 41439984, 2025). "In cells with the MTAP deletion, PMRT5 inhibitors and MTA exert a synergistic effect, enabling the selective destruction of cancer cells by reducing arginine methylation in histones and in other proteins regulating gene expression." (PMID 41465382, 2025). "More critically, specific genetic abnormalities, such as MTAP codeletion with the CDNK2A tumor suppressor gene, observed in approximately 15% of cancers, create an additional vulnerability to PRMT5 depletion." (PMID 40091834, 2025). "In preclinical studies on cell lines and xenograft models with MTAP gene deletion, IDE397 showed a cytotoxic effect on cancer cells and inhibited the growth of tumors." (PMID 41465382, 2025). "Baseline expression levels of CXCL9, CXCL10, and CXCL11 were relatively low and comparable between MTAP-WT and MTAP-KO CL1–0 and 786–0 cancer cells, as well as between CL1–5 Mock and MTAP-expressing cells." (PMID 41246302, 2025). "Furthermore, although MTA levels are elevated in MTAP-deleted cancers, the different levels of SAM, MTA, and other metabolic intermediates may vary across cells and tissues so that PRMT5 vulnerability may be impacted non-uniformly even in genetically defined backgrounds." (PMID 41339334, 2025). "Only 1.0% of 98 cancers in our heterogeneity TMA study and only 2 (4.9%) of 41 cancers in our “whole primary tumor analysis” showed a heterogeneous MTAP finding." (PMID 40664803, 2025). "The MTAP gene is located at 9p21.3, 30 kb apart from the CDKN2A gene, which is deleted in ≤ 15% of all human cancers." (PMID 40227771, 2025).
cancer (continued). "When MTDIA is administered and MTAP is inhibited, PRMT5-mediated histone methylation and intron splicing are competitively decreased, resulting in the restraint of cancer growth." (PMID 40519286, 2025). "Of the tumors with interpretable MTAP staining, 5,460 had data on ERG FISH and 10,418 cancers had ERG IHC data available." (PMID 40554389, 2025). "A recent example is the strong genomic dependency between MTAP (methylthioadenosine phosphorylase) deletion and PRMT5 inhibition in various cancers." (PMID 40087789, 2025). "Since MTAP‐deletion occurs at high frequency in almost 15% of all human cancer types, the synthetic lethality emerges MAT2A as a potential target for cancer treatment." (PMID 39309689, 2024). "This boundary is adjacent to the TADs containing the cancer genes CDKN2A, CDKN2B, and MTAP, all of which are tumor suppressors, and this boundary is located within a fragile site region (FRA9C)." (PMID 38758740, 2024). "Methylthioadenosine phosphorylase (MTAP), which catalyzes the degradation of 5′-deoxy-5′methylthioadenosine (MTA), is downregulated in many cancer entities." (PMID 39768204, 2024). "Mouse studies here predict efficacy as an anticancer agent in combination with MAT2a inhibitors for cancers of MTAP+/+ and MTAP−/− genotypes." (PMID 38000655, 2024). "LEF1, WT1 and BCL11B copy number abnormalities were reported from the TARGET study of 2471 pediatric cancer patients whereas in our group we found CDKN2A, CDKN2B and MTAP harboring most copy number variations." (PMID 38459434, 2024). "Copy number deletions of cancer suppressor genes (including CDKN2A/B, FOCAD, NF2, etc.)are always accompanied by adjacent functional genes (including MTAP, MLLT3, etc.)deletion that synergistically contributes to oncogenesis." (PMID 37033966, 2023). "For instance, the methylthioadenosine phosphorylase (MTAP), which catalyzes the first step in MTA's conversion into methionine, is commonly found defective in many cancer cell lines." (PMID 35083422, 2022). "Tumors that have MTAP and p16 co-deletion are sensitive to inhibition of MAT2A and that makes MAT2A an attractive lethal target for MTAP-deleted cancers." (PMID 36572880, 2022). "MTAP and p16/CDKN2A are two adjacent genes located at the 9p21 locus and homozygously co-deleted in approximately 15% of all human cancers." (PMID 35631199, 2022). "It has been shown that deletion of MTAP in cancer cells is common due to its proximity to CDKN2A, a commonly deleted gene in cancer." (PMID 35744905, 2022). "Methylthioadenosine phosphorylase (MTAP), a key enzyme in the methionine salvage pathway, is lost in almost all cancers." (PMID 34069168, 2021). "The genomic loci of type I interferon gene cluster, located ~320 kb upstream of MTAP on 9p21, is often co-deleted with CDKN2A/MTAP in a subset of cancers." (PMID 34556668, 2021). "Elevated MTA concentrations in MTAP−/− cancer cells provide partial inhibition of PRMT5, which would be enhanced in terms of cancer cell lethality when combined with an inhibitor of PRMT5 directly or with an inhibitor of MAT2A, which supplies SAM for PRMT5." (PMID 33893330, 2021). "Approximately 9.2% of cancers exhibited homozygous co-deletion of CDKN2A and MTAP, 3.7% of cancers had CDKN2A HD with wildtype or heterozygous MTAP, and 0.1% of cancers had MTAP HD with wildtype or heterozygous CDKN2A." (PMID 34556668, 2021). "Although MTAP deletion frequency is more rare in CRC than in other cancers, some CRC cell lines have been shown to have significantly increased MTAP and MAT2A expression, indicating increased reliance on these metabolic pathways." (PMID 33893330, 2021). "A potential therapeutic angle of this phenomenon was exposed in a synthetic lethal approach that identified PRMT5 as a vulnerability of cancers with MTAP deletion, because the elevated MTA levels in these cancers already limit necessary PRMT5 activity." (PMID 32276408, 2020).
cancer (continued). "Consistent with what previously demonstrated in other cancer types,24, 25, 33, 34MTAP‐negative MM cells showed a significantly higher mean intracellular MTA level compared with that of MTAP‐positive cells." (PMID 32301278, 2020). "To explore at the molecular level the proliferative role of PRMT5 in MTAP‐deleted MM cells, we analysed the effect of PRMT5 knock‐down on the expression of genes involved in cancer cell growth." (PMID 32301278, 2020). "Finally, the function and physiological role (if any) of MTAP alternatively spliced transcript is unknown, but it is frequently deleted in many types of cancer making its presence in 95% of MPMs (i.e., 38/40 tumors) an intriguing avenue for additional exploration." (PMID 20485525, 2010). "Among ERG negative cancers, Ki67LI was 1.7 ± 0.1 in 584 tumors with 1+, 2.7 ± 0.1 in 1,103 tumors with 2+, and 3.3 ± 0.1 in 747 tumors with 3+ MTAP staining (p < 0.0001)." (PMID 40554389, 2025). "In ERG negative cancers, high MTAP expression was related to deletions of PTEN (p < 0.0001), 8p21 (p < 0.0001), 5q21 (p = 0.0049), 12p13 (p = 0.0274), and 17p13 (p = 0.001)." (PMID 40554389, 2025). "In both ERG negative and ERG positive cancers, four different multivariate analyses were performed to evaluate the clinical relevance of MTAP expression in different scenarios." (PMID 40554389, 2025). "While MTAP deletion is not sufficient to affect splicing fidelity, it renders these cancers vulnerable to further inhibition of Prmt5 activity either by genetic mutations or small molecule inhibitors." (PMID 39862967, 2025). "Samples with adjacent normal and cancerous glands showed that both an increased and a decreased MTAP expression were possible in cancer cells as compared to normal prostate glands." (PMID 40554389, 2025). "This MTAP deletion-induced vulnerability is extend to the MAT2A, the upstream enzymes of PRMT5, and three kinds of MAT2A inhibitor (AG-270, S-095033, and IDE-397) are currently in the phase I clinical trials for the therapy of MTAP-deleted cancers." (PMID 41445748, 2025). "Moreover, due to the close location of the MTAP and CDKN2A genes, their co-deletion is often observed in cancers." (PMID 41465382, 2025). "The MTAP gene is located at 9p21.3, only 30 kb apart from the cyclin dependent kinase inhibitor 2A (CDKN2A) gene which is homozygous deleted in up to 15% of all human cancers." (PMID 39668577, 2025). "For this, we used an MTAP/CDKN2B-AS1 deletion (MA-del) assay to examine various EJ outcomes via the chromosomal deletion rearrangement of the CDKN2A gene, a common deletion rearrangement found in various cancer types 51,52." (PMID 41285797, 2025). "For instance, large-scale RNA interference data from the Cancer Dependency Map (DepMap) and Project Drive led to the discovery of PRMT5 as a promising target in 9p21.3−/− cancers through its synthetic lethal interactions with MTAP deletion." (PMID 39910293, 2025). "MTAP is often homozygously deleted as a consequence of a passenger event, in which neighbor gene cyclin-dependent kinase inhibitor 2A (CDKN2A) is deleted, with a frequency of approximately 15% in cases of pan-cancer and exceeding 50% in certain cancer types." (PMID 40590219, 2025). "The high expression of MAT2A and PRMT5 in cancer cells with a homozygous deletion of the MTAP gene appears to be a negative predictive factor of treatment with PRMT5 and MAT2A inhibitors." (PMID 41465382, 2025). "Cancer cells with a homozygous deletion of the MTAP gene do not degrade MTA, which is accumulated in cells and inhibits the activity of the PRMT5 enzyme." (PMID 41465382, 2025). "In cancer cells, an increase in MAT2A expression is observed, which weakens the inhibitory effect of MTA on PRMT5 and slightly increases the histone methylation process in cells with MTAP deletion." (PMID 41465382, 2025).
cancer (continued). "Over the years, several other human cancers including leukemias and solid tumors showed absence of MTAP, prompting researchers to dive deeper into comprehending its role in oncogenesis." (PMID 41439984, 2025). "MTAP expression provided significant prognostic value beyond the established parameters in all of the described scenarios in the subgroup of ERG negative cancers but not in ERG positive cancers." (PMID 40554389, 2025). "MTAP was found to be absent in certain cancer cells that also showed increased dependency on methylthio groups for cell division, thus establishing its role as an important metabolic enzyme." (PMID 41439984, 2025). "To build on these findings, we conducted an integrative analysis of complete homozygous deletion and low expression of MTAP using data from two major cancer genomics resources, the Cancer Cell Line Encyclopedia (CCLE DepMap Public 24Q4) and The Cancer Genome Atlas (TCGA) through cBioPortal." (PMID 41439984, 2025). "The MTAP gene is located at the 9p21.3 locus, which is a deletion hotspot in ALL, as well as in solid tumors, with a high prevalence in pancreatic (18.4%), biliary tract (15.6%), and lung (14.3%) cancers." (PMID 40603833, 2025). "These drugs showed no robust selectivity for MTAP-null cancers, making second-generation inhibitors more suitable for targeting MTAP." (PMID 41439984, 2025). "As these mechanisms are conserved from yeast to humans, MTAP inhibition might also induce autophagy in humans and be a mechanism for MTDIA-mediated death of cancer cells." (PMID 40375736, 2025). "In GBM cells, MTAP knockout did not increase cell proliferation, migration, and invasion as observed in other cancers." (PMID 41439984, 2025). "There was a strong positive association between AR expression and MTAP expression in all cancers as well as in subsets of ERG negative and ERG positive cancers (p < 0.0001 each)." (PMID 40554389, 2025). "A unique mechanism, associated with the accumulation of MTA, which is not degraded by MTAP, sensitizes cancer cells to PRMT5 and MAT2A inhibitors." (PMID 41465382, 2025). "Discovering the synthetic lethal interaction between MAT2A and MTAP, it was proposed that MAT2A inhibitors could be a promising strategy to suppress the proliferation of MTAP‐deleted cancers." (PMID 39309689, 2024). "Approximately 10% of all human cancers exhibit frequent deletions of both CDKN2A and MTAP." (PMID 39315676, 2024). "These specific metabolic flux–related genes, such as DNM2 (endocytosis), APOC1 (lipid transport), MRI1 (L-methionine salvage), MTAP (NAD salvage), and SLC29A1 (nucleoside import), indicate that the cancer progenitor cells represent hubs of metabolic trafficking activities." (PMID 38649187, 2024). "Several tumour suppressor genes such as MTAP, CDKN2A and B, mapped to the locus 9p21, were shown to present with homozygous or heterozygous deletions accompanied by poor prognosis in multiple forms of cancer." (PMID 38164368, 2024). "The first generation of PRMT5 inhibitors that were developed did not demonstrate sufficient selectivity for MTAP-deleted cancer cell lines and resulted in intolerability from dose-limiting myelosuppression." (PMID 39337530, 2024). "This disparity arises due to the absence of 5-methylthioadenosine phosphorylase (MTAP), a crucial enzyme in the methionine salvage pathway, within cancer cells." (PMID 38923999, 2024). "Subsequent genomic profiling, utilizing DNA-based cancer panel sequencing (Oncomine Comprehensive Assay Plus), revealed a homozygous deletion of the CDKN2A and MTAP gene locus but did not identify further actionable mutations." (PMID 39085487, 2024). "Those date all indicated that human cancers that do not express MTAP protein exhibit an apparent reduction of PRMT5 activity relative to MTAP‐expressing tumors." (PMID 39711357, 2024).